MSTN (myostatin)
Diseases named in the same sentence as MSTN in open-access papers (continued):
Sharing a sentence is not in itself a finding about the gene and the disease.
MSTN also shares sentences with these, for which no sentence is quoted: AIDS (8 papers); liver dysfunction (6); amyotrophic lateral sclerosis (5); coronary artery disease (4); hypertrophy (4); ovarian hyperstimulation syndrome (4); Glucose intolerance (3); inflammatory bowel disease (3); acute myocardial infarction (2); acute-on-chronic liver failure (2); age (2); aortic stenosis (2); bladder cancer (2); chronic kidney failure (2); colorectal cancer (2); Crohn disease (2); deficiencies (2); end stage renal disease (2); facioscapulohumeral muscular dystrophy (2); Genetic obesity (2); glucose metabolism disorders (2); Hypercholesterolemia (2); hyperlipidemia (2); infarction (2); knee osteoarthritis (2); liver failure (2); maple syrup urine disease (2); medullary thyroid cancer (2); multiple sclerosis (2); oculopharyngeal muscular dystrophy (2).
A further 81 diseases each share a sentence with MSTN in 2 papers or fewer.